DDX20 (DEAD-box helicase 20)
Diseases named in the same sentence as DDX20 in open-access papers (continued):
Sharing a sentence is not in itself a finding about the gene and the disease.
tumor (11 papers, 2014 to 2025). "In this study, we reported that the DDX20 expression had a strong molecular connection with immune infiltrate statuses such as Treg, macrophages, DC, and other tumor-associated immune cells." (PMID 36246406, 2022). "Other affected genes are related to apoptosis (Ddx20, Ikbip), integrin-associated signal transduccion (Cd47), stress protein with antioxidant-associated tumor suppressive function (Tp53inp1/Trp53inp1), calcium signaling (Stim1), as well as those related to proliferation and survival (Lin28a)." (PMID 30742662, 2019). "Remarkably, we found higher transcript levels of PyMT tumor antigens (Hspa4l, Lyar, Ddx20, Acrbp) in these cells of PyMT-PAR2G37I relative to PyMT-PAR2WT mice, suggesting increased uptake of tumor cell debris, which contains various nucleic acid species." (PMID 40694429, 2025). "The role of DDX20 in tumors has also received considerable attention as it functions not only as a double-sided tumor suppressor and promoter but also as a potential antitumor drug target and marker." (PMID 37894677, 2023). "Recently, the DEAD-box helicase 20 (DDX20) protein was identified as a downstream target of DAPK that leads to the tumor suppressor function of DAPK in HCC." (PMID 37189787, 2023). "We also evaluate the effect of genetic alterations of DDX20 on dysfunctional T-cell phenotypes, cytotoxic T-cell levels (CTLs), and tumor patient outcomes using the Query module in TIDE." (PMID 36246406, 2022). "Next, we found positive, statistically significant correlations between expression of DDX20 and T dysfunction in 5 tumor cohorts." (PMID 36246406, 2022). "High DDX20 expression is positively correlated with tumor stage and health condition and predicts a poor prognosis for HCC patients." (PMID 36246406, 2022). "To assess the value of DDX20 gene as an immuno-tumor biomarker, we used the TIDE algorithm, base TIDE framework (tide." (PMID 36246406, 2022). "Thus, DDX20 acts either as an oncogenic factor promoting tumor development or as a tumor suppressor inhibiting tumor progression." (PMID 37894677, 2023). "DDX20 expression has previously been identified to vary in tumor tissues." (PMID 37894677, 2023). "Thus, we detected the methylation level in UALCAN and found a decreasing trend of the promoter methylation level of DDX20 with increasing tumor grade and stage." (PMID 36246406, 2022). "However, little is known about DDX20 expression, clinical values, and the relationship with tumor microenvironment in HCC." (PMID 36246406, 2022). "Therefore, it is inferred that DDX20 can function as a tumor suppressor." (PMID 37894677, 2023). "Here, we systematically analyzed the relationships between the DDX20 expression level and HCC patients' clinical outcomes, tumor multiomics, and microenvironment using publicly available transcriptome data." (PMID 36246406, 2022). "To investigate DDX20 essentiality in HCC cells, we leveraged CGPE, which can generate genetic dependencies of mRNA in tumor cells by pooled RNAi or CRISPR screening data." (PMID 36246406, 2022). "Other targets of up regulated miRNAs in different treatment conditions also includes proteins that inhibit tumor progression, such as DNMT3A, FADD, pTEN, FOXO3, DDX20 and PA2G4 (EBP1)." (PMID 24387052, 2014). "Therefore, DDX20, the downstream gene of DAPK1, appears to be both an oncogene and an oncogene suppressor in different tumor types." (PMID 36290392, 2022).
infectious disease (1 paper, 2025). A disorder directly resulting from the presence and activity of a microbial, viral, or parasitic agent in humans. "In the CAPM group, we identified activation of DDX20- and RBBP4-related infectious disease response pathways, marked by C3 phosphorylation at S715, which is a well-known pro-inflammatory molecule." (PMID 40842862, 2025).
DDX20 also shares sentences with these, for which no sentence is quoted: esophageal adenocarcinoma (2 papers); infection (2); myopathy (2); non-Hodgkin lymphoma (2); prostate carcinoma (2); T-cell lymphoma (2); Alzheimer disease (1); amyotrophic lateral sclerosis (1); COVID-19 (1); depression (1); diffuse large B-cell lymphoma (1); hepatitis B virus infection (1); invasive breast carcinoma (1); leukoplakia (1); motor neuron disease (1); muscular atrophy (1); neurodegenerative disease (1); neurological diseases (1); oropharyngeal cancer (1); oropharyngeal squamous cell carcinoma (1); pancreatic cancer (1); primary open-angle glaucoma (1); renal cell carcinoma (1); tumor of brain (1).